UMOD (uromodulin)
Diseases named in the same sentence as UMOD in open-access papers (continued):
Sharing a sentence is not in itself a finding about the gene and the disease.
chronic kidney disease (continued). "Individuals (n = 485) were selected based on presence of the GWAS risk haplotype and chronic kidney disease (CKD) in the ARIC Study and on the extremes of of the UMOD gene product, uromodulin, in urine (Tamm Horsfall protein, THP) in the Framingham Heart Study (FHS)." (PMID 22693617, 2012). "Diminished expression of uromodulin was reported in different types of renal diseases such as diabetic nephropathy and chronic kidney disease (CKD) and may indicate pathophysiological changes in CKD." (PMID 24790760, 2014).
Hypertension (60 papers, 2010 to 2025). The presence of chronic increased pressure in the systemic arterial system. "Of the numerous loci and genes implicated in the pathophysiology of hypertension, uromodulin has shown promise as a new pharmacological target." (PMID 39259220, 2024). "The last few years have seen a shift of focus from genetic association to mendelian randomisation and uromodulin-salt interaction studies, thus confirming the causal role of uromodulin in blood pressure regulation and hypertension." (PMID 39259220, 2024). "Considering hypertension's status as a significant risk factor for various cardiovascular events, uromodulin emerges as a potential biomarker extending beyond renal function." (PMID 39049957, 2024). "UMOD has been shown to be a multi-functional protein, which has a causal role in the pathophysiology of hypertension." (PMID 39259220, 2024). "In non-Hispanic White participants, the rs4293393 risk variant was associated with significantly increased uromodulin and increased risk of hypertensions (rs4293393; OR: 1.03, 95% CI: 1.05–1.05, P = 2.11 × 10–6)." (PMID 39259220, 2024). "We examined the association between pre-existing hypertension and spot uromodulin concentration in a cohort of pregnant women." (PMID 38236469, 2024). "Genetic human studies of the past two decades have proposed a strong relationship of UMOD gene variants with sodium sensitivity and hypertension." (PMID 38211973, 2024). "Single nucleotide polymorphisms in the UMOD gene were associated with hypertension, and conversely, variants with lower UMOD levels were associated with a lower risk of hypertension." (PMID 39049957, 2024). "Taken together, these results provide valuable insights into the complex interplay between uromodulin, kidney function, and blood pressure regulation, shedding light on the potential mechanisms underlying hypertension." (PMID 37835820, 2023). "A pathogenic mutant of UMOD would possibly cause the dysregulation of glomerular renal filtration, resulting in severe hypertension." (PMID 36140271, 2022). "It indicates that a common genetic basis of urine uromodulin levels with higher risk of CKD and hypertension extends to circulating uromodulin levels and identifies kidney cell type–specific regulation of uromodulin expression as a mechanism." (PMID 35446786, 2022). "The image of uromodulin being implicated in electrolyte channel transporting had brought forth the role of uromodulin in hypertension." (PMID 36140271, 2022). "Our results based on different methods and datasets strengthen the theoretical support for further well-designed prospective randomized clinical trials to verify the causal association of uromodulin and hypertension, larger than those that came before them." (PMID 34540925, 2021). "Serum uromodulin was significantly associated with the lower risk of hypertension [0.978 (0.972–0.984)] in Hanzhong Adolescent Hypertension Study cohort." (PMID 34869624, 2021). "A study demonstrated that the activation of renal sodium cotransporter NKCC2 in transgenic mice potentially links the UMOD variants and hypertension." (PMID 33377622, 2021). "Genome-wide association studies have identified UMOD variants to be associated with renal function, chronic kidney disease and hypertension." (PMID 34870708, 2021). "We aimed to examine the associations of serum uromodulin levels and its genetic variants with longitudinal blood pressure (BP) changes and hypertension incidence/risk." (PMID 34869624, 2021). "Another study demonstrated an inverse association of serum uromodulin with arterial hypertension in a large population-based study." (PMID 33768217, 2021). "One study showed that higher serum uromodulin concentration was associated with a beneficial metabolic profile, lower prevalence rates of arterial hypertension, diabetes mellitus, heart failure and a lower risk for 10-year mortality." (PMID 33768217, 2021).
Hypertension (continued). "We here analyzed the association of serum uromodulin (sUmod) with arterial hypertension and vasoactive hormones in a population-based study." (PMID 32764816, 2020). "Uromodulin has been associated with arterial hypertension in genome-wide association studies, but data from clinical and preclinical studies are inconsistent." (PMID 32764816, 2020). "In conclusion, higher levels of urinary uromodulin are associated with lower odds of hypertension-attributed CKD." (PMID 31065383, 2019). "Uromodulin is associated with hypertension and other cardiovascular disorders in humans and preclinical models." (PMID 28348009, 2017). "In the GWAS in Icelandic and Dutch populations, rs4293393 near UMOD was reported to influence the adaption of the kidney to age-related risk factors of kidney diseases, including hypertension and diabetes." (PMID 28361944, 2017). "For instance, a previous GWAS study identified a single SNP in the upstream end of the uromodulin gene (UMOD) associated with blood pressure regulation as well as hypertension." (PMID 29109301, 2017). "Another single nucleotide polymorphism (SNP) in the promoter region of UMOD gene, rs13333226, was reported to be associated with hypertension, and serum uric level." (PMID 27938332, 2016). "First, a GWAS identified a locus in the 5′ region of UMOD gene whose minor allele is associated with a lower risk of hypertension." (PMID 25163389, 2014). "Using an extreme case-control strategy, we have discovered a SNP in the promoter region of the uromodulin gene (UMOD) to be associated with hypertension (minor allele protective against hypertension)." (PMID 21082022, 2010). "We show in the BRIGHT, HERCULES and GRECO (low sodium diet) that the minor allele of rs13333226 (associated with a lower risk of hypertension) is consistently associated with lower urinary uromodulin excretion." (PMID 21082022, 2010). "We have identified and validated a SNP upstream of the uromodulin (UMOD) gene whose minor allele is associated with a lower risk of hypertension." (PMID 21082022, 2010). "The exclusive expression of uromodulin in the thick portion of the ascending limb of Henle suggests a putative role of this variant in hypertension through an effect on sodium homeostasis." (PMID 21082022, 2010). "Uromodulin is a nephron-derived protein that is associated with hypertension and kidney diseases." (PMID 38236469, 2024). "Additionally, different polymorphisms of UMOD have been shown to contribute to cardiorenal function in patients with hypertension and cardiovascular disease." (PMID 38500750, 2024). "Some studies have proposed that urinary uromodulin may be associated with an increased risk of hypertension and CKD." (PMID 37835820, 2023). "In addition to contributing to kidney damage and aging-related lesions, the link between UMOD variants and hypertension has been demonstrated in a mouse model with increased uromodulin expression based on a gain-of-function mechanism." (PMID 37835820, 2023). "Patients with low serum uromodulin concentrations may benefit from intensified control of vascular risk factors such as glycemia, dyslipidemia, and hypertension." (PMID 37835820, 2023). "However, known variants in the UMOD gene such as rs1333226 (g.137485318T>C) and rs4293393 (c.-39-2490T>C) have been associated with hypertension and CKD among Africans." (PMID 38633331, 2023). "Extensive research in multiple disciplines has underscored the biological significance of the top UMOD gene variants, which have also been associated with hypertension and kidney stones, thus highlighting the diverse and significant impact of uromodulin on kidney-related conditions." (PMID 37835820, 2023). "We focus on possible genetic variants within the uromodulin gene, which could improve and widen treatment choices for hypertension management." (PMID 36378920, 2022).
Hypertension (continued). "Besides, we further assessed the causal effect of uromodulin on hypertension, utilizing the open data showing the association between SNPs and sUMOD." (PMID 34540925, 2021). "Besides CKD-related phenotypes, a recent GWAS has also reported the association between common variants of the UMOD gene and hypertension." (PMID 34828293, 2021). "Furthermore, our study also showed that serum uromodulin level was significantly associated with hypertension and its subtypes and grades." (PMID 34869624, 2021). "In addition, 2,210 subjects from the cohort of Hanzhong Adolescent Hypertension Study were used to investigate the relationships between serum uromodulin levels and the risk of hypertension." (PMID 34869624, 2021). "Furthermore, data are scarce about the relationship between serum uromodulin levels and the risk of hypertension." (PMID 34869624, 2021). "Future studies are needed to clarify the associations of salt, uromodulin and hypertension." (PMID 34363725, 2021). "In this study, we tried to use two-sample MR methods to unveil the causal effect of uromodulin on hypertension, systolic blood pressure (SBP), and diastolic blood pressure (DBP) using increasingly available public genome-wide association studies (GWAS) datasets." (PMID 34540925, 2021). "Therefore the causal effect of uromodulin on hypertension requires a new strategy in order to be investigated." (PMID 34540925, 2021). "In addition, prior studies showed that genetic variants in the UMOD gene were associated with BP phenotypes and hypertension." (PMID 34869624, 2021). "In addition, gene-based analyses supported the associations of uromodulin gene with the longitudinal BP changes and hypertension incidence in Baoji Salt-Sensitive Study cohort." (PMID 34869624, 2021). "In addition, we also used our large cross-sectional cohort to explore the possible relationships between serum uromodulin levels and the risk of hypertension." (PMID 34869624, 2021). "More than 50 genetic variants have been identified that are potentially associated with the decline of kidney function and the development of hypertension and renal injury in various studies, among which the most frequently identified gene variants are UMOD, MYH9, APOL1, SHROOM3, RAB38, and DAB2." (PMID 33377622, 2021). "Furthermore, our study comprehensively examined the associations of serum uromodulin levels with hypertension and its subtypes and grades." (PMID 34869624, 2021). "Single nucleotid polymorphisms in the UMOD promoter region increasing uromodulin levels are associated with hypertension, and the UMOD rs13333226 minor G allele interrelates with a reduced urinary uromodulin excretion and a decreased risk of arterial hypertension." (PMID 32764816, 2020). "Higher levels of urinary uromodulin are associated with lower odds of hypertension-attributed CKD." (PMID 31065383, 2019). "Uromodulin is an example of a novel gene for hypertension identified from genome-wide association studies, currently the basis of a clinical trial to reposition loop diuretics in hypertension management." (PMID 29881931, 2018). "For example, variants of the UMOD gene that was discovered to be associated with hypertension in a GWAS have the potential to predict the antihypertensive response to loop diuretics, and a clinical trial is currently planned (British Heart Foundation Clinical Study CS/16/1/31878)." (PMID 28161100, 2017). "These variants of the UMOD promoter lead to increased UMOD expression and secretion which results, by influencing salt reabsorption in the kidney, to increased risk of developing hypertension and CKD." (PMID 25409434, 2014). "However, the overall message is that lack of uromodulin causes decreased BP that is resistant to dietary salt due to a Bartter-like, urinary salt-wasting phenotype, while unregulated uromodulin excess causes hypertension due to increased tubular Na+ reabsorption that is responsive to furosemide." (PMID 38211973, 2024).
Hypertension (continued). "In addition, genome-wide association studies (GWAS) have demonstrated that common variants located in the promoter region of the UMOD gene are linked to CKD, GFR, kidney stone formation, and arterial hypertension, and increase UMOD expression and excretion of uromodulin in urine." (PMID 37835820, 2023). "For the outcome of hypertension, we observed that the elevated urinary uromodulin level could increase the risk of hypertension in dataset “ukb-b-14057” (Oodds ratio (OR) = 1.036, 95% CI, 1.029–1.043, P = 3.07E−26) and “ukb-b-14177” (OR = 1.036, 95% CI, 1.030–1.044, P = 3.29E−26)." (PMID 34540925, 2021). "Also, it might be relevant for CKD and hypertension where we demonstrated that UMOD risk variants are associated with increased uromodulin expression and urinary levels." (PMID 26673890, 2015). "Mutations in the UMOD gene have been associated with the risk of progressive CKD and other diseases, such as hypertension and kidney stones." (PMID 40428323, 2025). "We review the role of uromodulin, a protein exclusively expressed in the kidney, in blood pressure regulation and hypertension." (PMID 39259220, 2024). "Proteins angiotensinogen (AGT), albumin (ALB), APOL1, and uromodulin (UMOD) were associated with CKD and hypertension with high disease scores of 5.0 (100% confidence), 4.0 (80%), 3.9 (78%), and 3.8 (76%), respectively." (PMID 38402394, 2024). "Serum uromodulin was inversely associated with the development of CKD, even after adjustment for patient age, sex, genotype of the identified polymorphism, hypertension, diabetes status, and eGFR." (PMID 39061561, 2024). "In a urinary proteomic study among 56 patients with hypertension and 19 controls, Matafora et al8 found that patients with hypertension had higher levels of urinary uromodulin, which regulates water and salt balance and BP." (PMID 38445514, 2024). "In the following lines, we present the main preclinical, genetic and clinical studies linking uromodulin to hypertension and sodium sensitivity." (PMID 38211973, 2024). "Genetic studies have associated common variants of uromodulin with kidney function, risk of CKD and hypertension." (PMID 38236469, 2024). "The finding that the gene collapsing analyses in essential hypertension identified variation in genes (PKD1, PKD2, COL4A4, UMOD, CACNA1D, and NR3C2) that are possible causes of undiagnosed secondary hypertension is worthy a special comment." (PMID 37059828, 2023). "Further research into molecular insights on regulation, secretion, and post-translational modifications will make uromodulin a potential target for studies to discover new druggable targets for hypertension and CKD." (PMID 36378920, 2022). "The UMOD variants associated with risk of hypertension and CKD in the general population increase the expression and urinary excretion of uromodulin." (PMID 35881244, 2022). "The connection between the urinary peptidome of pregnant animals (rats) and hypertension was found, and the role of the glycoprotein uromodulin in hypertension was outlined." (PMID 34538010, 2022). "This study provides novel insights into the cross−talk between TAL and the collecting duct, and indicates that the modulation of uromodulin is a promising approach for diuresis and hypertension treatment." (PMID 36012675, 2022). "In these GWAS, the UMOD alleles associated with higher uromodulin expression/levels are associated with increased risk of CKD, hypertension, and hyperuricemia, whereas they are protective for kidney stones." (PMID 35881244, 2022). "It featured significantly lower uromodulin expression levels, which caused higher eGFRs and in turn lowered the risk of CKD, the formation of kidney stones, and hypertension." (PMID 36140271, 2022).